NKX2-5 (NK2 homeobox 5)
Diseases named in the same sentence as NKX2-5 in open-access papers (continued):
Sharing a sentence is not in itself a finding about the gene and the disease.
myocardial diseases (1 paper, 2024). "The two genes uniquely identified for single AF events have been shown important for myocardial diseases and cardiac abnormalities, coding for functions found to be central in malformation in heart (NKX2-5) and myosin (MYH7)." (PMID 38725839, 2024).
Obesity (1 paper, 2023). Accumulation of substantial excess body fat. "Moreover, the expression of Nkx2-5, a crucial regulator of heart development, was correlated with maternal obesity in fetal mice and persisted in adult hearts." (PMID 37571325, 2023).
ovarian carcinoma (1 paper, 2020). A malignant neoplasm originating from the surface ovarian epithelium. "CHRD, NKX2-5 were also co-expressed in bladder and ovarian cancer datasets whereas BAMBI was only reported in breast and lung datasets." (PMID 31973134, 2020).
Patent foramen ovale (1 paper, 2022). Failure of the foramen ovale to seal postnatally, leaving a potential conduit between the left and right cardiac atria. "However, upon closer examination, it was determined that Nkx2-5 haploinsufficiency did in fact result in a low frequency of ASDs and an increased incidence of patent foramen ovale (PFO)." (PMID 35835508, 2022).
prostate adenocarcinoma (1 paper, 2023). "There is age-related Nkx2–5 methylation in normal prostate tissues and may predispose to prostate adenocarcinoma." (PMID 38110859, 2023).
stable angina (1 paper, 2018). "In a previous clinical study, increased expression of specific cardiac markers (Nkx2-5, gata-4, and mef2c) in PBMNCs, and increased number of CD34+/CXCR4+ and CD34+/CD117+ stem cells in PB were observed in ST-elevated MI patients compared to patients with stable angina and healthy Controls." (PMID 30485279, 2018).
Truncus arteriosus (1 paper, 2016). A single arterial trunk arises from the cardiac mass. "VSDs as well as ASDs were seen in Nipbl+/-; Nkx2-5+/- hearts, in several cases in combination; and two cases of persistent truncus arteriosus (PTA) were also observed." (PMID 27606604, 2016).
Venous malformation (1 paper, 2015). A vascular malformation resulting from a developmental error of venous tissue composed of dysmorphic channels lined by flattened endothelium and exhibiting slow turnover. "Interestingly, previous documentation of other venous malformations have been reported in NKX2-5 mutations." (PMID 25742962, 2015).
Heart Disease (17 papers, 2007 to 2023). "We therefore tested a panel of five NKX2-5 point mutations in the homeodomain associated with heart disease: Q187H, N188 K, R189G, R190H and Y191C." (PMID 27683156, 2016). "Several SFRP4-targeted genes, such as MYH6, MYH7, TNNT2 and NKX2-5, contributed to different types of heart diseases." (PMID 32423033, 2020). "Our results for NKX2-5 by using a yeast-based assay to determine function suggest that different haplotypes can lead to different cardiac disease phenotypes." (PMID 17592645, 2007).
cancer (15 papers, 2008 to 2025). A tumor composed of atypical neoplastic, often pleomorphic cells that invade other tissues. "The expression of HAND2 (heart- and neural crest derivatives-expressed 2) and TWIST1 (twist family bHLH transcription factor 1) was significantly upregulated, while the expression of NKX2-5 (NK2 Homeobox 5) was significantly downregulated in MSCs compared to cancer cell lines." (PMID 39621192, 2025). "MIR130A, which could inhibit the gene NKX2-5, could act as a miRNA of tumor-inhibiting to inhibit cancer cell proliferation, migration and dedifferentiation." (PMID 31126066, 2019). "The presence of dysregulated Nkx 2–5 is present in cancers such as ALL, because there it is working in a very different microenvironment and with different regulatory genes such as Mef2c-Nkx2–5 complex, which plays oncogenic role." (PMID 38110859, 2023). "Seminal work published by Kwabi-Addu and his coauthors in the Clinical Cancer Research showed that methylation of GSTPi, RARβ2, RASSF1A, NK2 homeobox 5 (NKX-2-5), and estrogen receptor 1 (ESR1) tumours suppressor genes in prostate tissues is age-independent." (PMID 27891254, 2016). "Six multiple interacting TFs were found to have common functions between immune systems and cancer tissues, including CEBPGAMMA:NKX25:PLZF, CEBPGAMMA:PAX4:PLZF, CP2:NFY:PAX4, FOXJ2:PAX4:POU3F2, CEBPGAMMA:PAX4:PLZF, and FOXJ2:HNF3:PAX4." (PMID 20085649, 2010). "As it works together with Nkx2–5 which is expressed in CM cells, MYOCD may have a role in maintaining the benign nature of cardiac myxoma and in preventing the occurrence of malignant tumors in cardiac tissue." (PMID 38110859, 2023).
tumor (12 papers, 2009 to 2025). "We used CCK‐8 assays, colony formation studies, and tumor transplantation models to quantitatively assess the impacts of NKX2‐5 and LHX1 on ESCC cell proliferation." (PMID 40307990, 2025). "NPCEDRG is a novel tumor suppressive gene and has potential binding sites for Nkx2–5, thus inducing cell differentiation, controlling cell growth and regulating the cell cycle." (PMID 38110859, 2023). "Notably, concurrent inhibition of UHRF1 and DNMTs impedes tumor growth by suppressing NKX2‐5 and LHX1 expression." (PMID 40307990, 2025). "Thus, compared to normal tissues, tumor tissues show greater overall enrichment of NKX2‐5 and LHX1 binding." (PMID 40307990, 2025). "Additionally, these findings further validate that simultaneous inhibition of both UHRF1 and DNMTs exhibits anti‐tumor activity by effectively suppressing the expression of NKX2‐5/LHX1." (PMID 40307990, 2025). "Some studies have pointed to the dysregulated expression of Nkx2–5 in tumor development." (PMID 38110859, 2023). "Some studies have hinted towards the possible role of Nkx2–5 in this tumor development." (PMID 38110859, 2023). "Our findings revealed that silencing NKX2‐5 or LHX1 significantly inhibited ESCC cell proliferation, colony formation, and tumor growth." (PMID 40307990, 2025). "This intricate interplay forms a positive transcriptional feedback loop between NKX2‐5/LHX1 and UHRF1, thus promoting the overexpression of all three genes and ultimately facilitating tumor growth." (PMID 40307990, 2025). "HAND1/2 plays pivotal roles by interacting with Nkx2–5 and GATA4: it encourages proliferation alongside Nkx2–5 and promotes differentiation with GATA4, while also acting as a tumor suppressor (TS)." (PMID 38110859, 2023). "Our results demonstrated that combined treatment with NSC232003 and SGI‐1027 led to a more pronounced downregulation of NKX2‐5/LHX1 expression and superior tumor growth inhibition than either inhibitor alone, highlighting the potential of this combinatorial therapeutic approach for ESCC management." (PMID 40307990, 2025). "Notably, two of these genes, NKX2‐5 and LHX1, were found to play pivotal roles in the oncogenic transformation of normal esophageal epithelial cells and ESCC tumor growth." (PMID 40307990, 2025).
infection (8 papers, 2016 to 2026). The state of being infected such as from the introduction of a foreign agent such as serum, vaccine, antigenic substance or organism. "The effects of Nkx2‐5 on chemokines production were confusing, given that expression of C‐X‐C motif chemokine ligand 8 was inhibited and C‐C motif chemokine ligand 5 augmented by Ad‐Nkx2‐5 infection." (PMID 27993833, 2016). "As immunohistochemical staining demonstrated, MMP2 and MMP9 expression in atherosclerotic lesions was substantially decreased in mice treated with Ad‐Nkx2‐5, compared to Ad‐EV‐treated controls, and Ad‐shNkx2‐5 infection significant increased the levels of MMP2 and MMP9." (PMID 27993833, 2016).
vasculopathies (1 paper, 2024). "Our data suggest a pivotal role for NKX2-5 in the phenotypic modulation of smooth muscle cells during pathological vascular remodeling and provide proof of concept for therapeutic targeting of NKX2-5 in vasculopathies." (PMID 38652537, 2024).
NKX2-5 also shares sentences with these, for which no sentence is quoted: myocardial infarction (14 papers); cardiovascular disease (7); ischemia (3); Atrioventricular canal defect (2); cardiac conduction disorders (2); congenital heart malformation (2); congestive heart diseases (2); diabetic cardiomyopathy (2); fibrosis (2); genetic disease (2); hypertrophy (2); hypothyroidism (2); left ventricular hypertrabeculation (2); myxoma (2); neuroendocrine neoplasm (2); ovarian yolk sac tumor (2); papillary thyroid carcinoma (2); skin squamous cell carcinoma (2); thyroid hypoplasia (2); Ventricular arrhythmia (2); viral infection (2); acute coronary syndrome (1); age (1); aortic coarctation (1); aortic stenosis (1); aortic valve stenosis (1); asplenia (1); athyreosis (1); atrial septal defect 2 (1); atrial tachycardia (1).
A further 54 diseases each share a sentence with NKX2-5 in 1 paper.